NQO1 (NAD(P)H quinone dehydrogenase 1)
Diseases named in the same sentence as NQO1 in open-access papers (continued):
Sharing a sentence is not in itself a finding about the gene and the disease.
cancer (continued). "The expression of TF-protein FOXL1 (a regulator of NT5E, TP53INP1, HPGD, FN1, OAS1 and NQO1) is connected with numerous cancer." (PMID 35617355, 2022). "NQO1-dependent anti-cancer drugs such as β-lapachone are attractive candidates for cancer therapy because several cancers, including cervix, breast, pancreas, colon, and lung, exhibit higher expression of NQO1 than adjacent tissues." (PMID 35897965, 2022). "Based on these findings, probe 1 can be applied in early diagnosis of cancers that overexpress NQO1." (PMID 35154500, 2022). "Recently, KP372-1 was also reported as a novel potential anticancer agent that targeted NQO1 to induce extensive reactive oxygen species (ROS) generation that amplified DNA damage, leading to cancer cell death." (PMID 36203459, 2022). "The nuclear translocation of the Nrf2 activates the ARE-gene cluster (including GCLC, Nqo1, and HO-1) facilitating ROS-mediated apoptosis in neuroinflammation ultimately leading to neurodegeneration and cell death in cancer cells." (PMID 35360165, 2022). "So, NQO1 expression inhibition can disrupt intracellular redox balance, such as ROS overproduction in cancer cells." (PMID 35720178, 2022). "In a variety of tumors, NQO1 has been shown to be overexpressed and capable of bioactivating certain quinone substrates, which means it is an ideal target for cancer treatment." (PMID 36338728, 2022). "The toxicity of dicoumarol against cancer cells seems to be mainly mediated by the mitochondrial production of ROS due to NQO1 inhibition." (PMID 36575479, 2022). "Although activation of NQO1 can act as a tumor suppressor, a “Janus” effect of NQO1 in cancer has been suggested." (PMID 36362202, 2022). "Individual NRF1, NRF2 and NQO1 expression within all cancer, immune and stromal cells are heterogenous in this closely-related cohort." (PMID 36359002, 2022). "For example, the elimination of indolequinones can be achieved under hypoxic environments with the aid of the DT-diaphorase NQO1, which is overexpressed in various cancer cells and plays a crucial role in bioreduction." (PMID 36096856, 2022). "Dicoumarol has been gaining interest in the cancer setting due to its action as an inhibitor of nicotinamide adenine dinucleotide phosphate (NAD(P)):(quinone acceptor) oxidoreductase 1 (NQO1), by competing with NAD(P)H at the pyridine nucleotide binding site." (PMID 36575479, 2022). "While not fully understood, this phenotype has been consistently reported for cancer cells where NQO1 is targeted for bioactivation." (PMID 35893874, 2022). "NQO1 is overexpressed in many cancers and is involved in carcinogenesis, drug resistance, and cancer progression." (PMID 36142607, 2022). "In cancer cells, NQO1 expression is heterogenous, displaying low, moderate and high expression within individual cases and, importantly, between analyses, potentially due to the patient genetic background or ubiquitous ROS sources within the tumor." (PMID 36359002, 2022). "It is reported that the role of NQO1 in cancer cells is to prevent excessive oxidative stress from damaging cells which is consistent with that in normal cells." (PMID 35720178, 2022). "In cancer, NQO1 is often highly expressed relative to normal tissue and there is ongoing research into therapies involving NQO1 substrate pro-drugs used to selectively target cancer cells." (PMID 35326683, 2022). "β-lapachone is a bioactivatable chemotherapeutic agent that directly targets cancer cell lines over-expressing NQO1, leading to the interruption of glycolytic metabolism and changes in the redox state of the cell." (PMID 34439319, 2021). "Understanding the complex mechanism and functioning of NQO1 in cancer studies reveals that this protein exhibits as both tumor suppressor and tumor promoter under different tools." (PMID 34833955, 2021).
cancer (continued). "Highly conjugated naphthyl fused benzimidazolequinone 2 leads to increased stability of reduced intermediates leading to specificity towards human cancer cell lines over-expressing NQO1." (PMID 34064312, 2021). "It has also been reported that NQO1 knockout mice showed sensitivity to carcinogens in the skin resulting in cancer." (PMID 34884772, 2021). "β-lap has been reported to induce multiple cell death mechanisms including autophagy, apoptosis and necrotic cell death in NQO1+-cancer cells." (PMID 34789190, 2021). "NQO1 is overexpressed in numerous human cancers, and our previous studies together with others demonstrate that β-lap has efficacy in tumor-selective cell growth control and produced promising preclinical results." (PMID 34676172, 2021). "Conversely, overexpression of NQO1 is cytoprotective, and known to drive metastasis, with overexpressed NQO1 commonly detected in late stage and poor prognoses cancers." (PMID 34679751, 2021). "Cancer cells, including cancer stem cells, often express high levels of NQO1 compared with healthy cells." (PMID 34107166, 2021). "NQO1 expression levels in these cancer cells were established previously by Western blot analysis, and shown to be sustained in cancer cells after β-lapachone treatment." (PMID 34439319, 2021). "Intracellular ROS production is crucial for cancer cell death, and our previous studies show that NQO1 metabolizes β-lap in a futile redox cycle manner to generate ROS in other solid cancer cells." (PMID 34676172, 2021). "Anti-cancer effect of bio-reductive drug beta-lapachon is enhanced by activating NQO1 with heat shock." (PMID 33710819, 2021). "NQO1 is a promising target for cancer detection, selective anticancer therapy, and provides multiple layers of protection to cells against carcinogenesis." (PMID 34833955, 2021). "On the other hand, NQO1 induction is used in cancer therapy because bio-reductive anticancer drugs (e.g., mitomycin C) are activated by NQO1." (PMID 34836129, 2021). "It is well-known that NQO1 is expressed at high levels in numerous human cancers, including breast, colon, cervix, lung, and pancreas, as compared with normal tissues." (PMID 33064289, 2021). "Many cancers overexpress the two-electron reductase NQO1, which can bioactivate the drug β-lapachone, inducing a futile redox cycle that liberates large amounts of reactive oxygen species and results in subsequent cell death." (PMID 34439319, 2021). "Tanespimycin (also known as 17-AAG) is a HSP90 inhibitor, and NQO1 expression is inversely correlated with 17-AAG IC50s in cancer cell lines." (PMID 33858332, 2021). "Among many therapeutic targets, NAD(P)H: quinone oxidoreductase 1 (NQO1) is an enzyme involved in cellular detoxifying reactions which has been recognized as a potential target for cancer treatment." (PMID 34439319, 2021). "Studies have shown that the expression of NQO1 is up‐regulated in many malignant tumors, such as melanoma, pancreatic cancer, intrahepatic cholangiocarcinoma, lung cancer, and breast cancer." (PMID 33841805, 2021). "It has been shown that the elevated levels of NQO1 can provide a means to restrict the effect of redox-activated prodrugs primarily to cancer cells." (PMID 34615851, 2021). "Our study supports the existing perception that β-lap is an NQO1 bioactivatable drug, and β-lap’s lethality stems from β-lap-induced futile redox cycling in NQO1+ cancer cells, producing oxidative DNA lesions and consequent PARP1- mediated necrotic cell death." (PMID 34789190, 2021).
cancer (continued). "β-lap’s therapeutic efficacy mainly stems from β-lap-induced futile redox cycling in NQO1+ cancer cells, producing oxidative DNA lesions and consequent cell death, while normal tissues are spared by low NQO1 expression." (PMID 34789190, 2021). "NQO1 overexpression in tumors has the advantage of preferentially killing cancer cells and sparing normal cells when anticancer drugs that are bioreductively activated by NQO1, such as β-Lapachone (β-lap), are used." (PMID 34676172, 2021). "As the activator of LPC, NQO1 plays an important role in the pharmacological activity of LPC in cancer therapy." (PMID 34790130, 2021). "Many solid tumors also over-express the obligatory two-electron reductase NAD(P)H:quinone oxidoreductase 1 (NQO1, also known as DT-diaphorase), which is a popular target for anti-cancer studies." (PMID 34064312, 2021). "The high amount of NQO1 in cancer cells is thought to help them cope up with oxidative stress, just as they do in healthy cells." (PMID 34833955, 2021). "β-Lapachone (ARQ761 in clinical form) selectively kill NADPH: quinone oxidoreductase 1 (NQO1)-overexpressing cancer cells." (PMID 34676172, 2021). "The ability of NQO1 to generate cytotoxic hydroquinones has been utilized as a strategy to target cancer cells with high NQO1 levels." (PMID 32007910, 2020). "Alternatively, in cancer cells with low NQO1 activity, an antioxidant approach is required to keep normal cells intact during long-term chemotherapy or radiotherapy." (PMID 32645959, 2020). "Collectively, our mechanistic study lays an essential foundation to establish KP372-1 as a promising chemotherapeutic agent against pancreatic and other NQO1-overexpressing cancers." (PMID 33214574, 2020). "These previous studies suggest that inducing detoxifying enzymes (including NQO1) through the Nrf2-Keap1 pathway can improve energy metabolism and be used to prevent cancer progression." (PMID 32645959, 2020). "These two probes not only have high selectivity and sensitivity against NQO1, but also have been successfully used in intracellular imaging, showing good potential in cancer diagnosis." (PMID 33005608, 2020). "Since NQO1 is overexpressed in cancer cells compared to levels in normal cells, β-lapachone can function effectively in cancer cells." (PMID 33261219, 2020). "One of the key intracellular regulators of the redox cycling of menadione is NQO1, which is overexpressed in various cancers." (PMID 33204397, 2020). "High expression of NQO1 is known to be a poor prognostic factor in several types of cancers, including hepatoblastoma, and NQO1 inhibition has been reported to sensitize multiple types of cancers to anticancer drugs." (PMID 32656360, 2020). "Using NQO1 as a predictive biomarker, this combination treatment strategy may reduce the impact of treatment on a patient’s lifetime exposure to IR, may cut the costs associated with cancer treatment, and potentially reduce the amount of time needed for therapeutic response." (PMID 32974194, 2020). "NQO1 seems to play a dual role in different pathological states: first, NQO1 is overexpressed in cancer cells, enhancing the cellular antioxidant capacity." (PMID 33153185, 2020). "Due to the role of PARP hyperactivation in the mechanism of action of β-lap, PARP inhibitors have been a central focus in improving the efficacy and reducing the toxicity of β-lap for use in NQO1(+) cancers." (PMID 32295316, 2020). "NQO1 and SOD are commonly overexpressed in various types of cancers and generally associated with aggressive growth, although in many primary tumors Mn-SOD activity is markedly reduced." (PMID 33204397, 2020). "Treatments involving dicumarol, an NQO1 inhibitor, potentiate the cytotoxic effects induced by chemotherapy drugs, such as cisplatin 9 or gemcitabine 10, on cancer cells; this result implies the involvement of NQO1 in cancer chemoresistance." (PMID 32922184, 2020).
cancer (continued). "Given their roles in cancer pathogenesis, redox homeostasis and the metabolic shift from glycolysis to oxidative phosphorylation (through activation of Nrf2 and NQO1) seem to be good targets for cancer therapy." (PMID 32645959, 2020). "Among BCR patients (n = 23) in our cohort, we noted 65% patients had decreased NQO1 levels and two thirds of them (10 out of 15) had higher stage cancer (stage 3a and b)." (PMID 31909204, 2020). "Taken together, these results indicated that an Nrf2-independent regulation of NQO1 expression possibly existed in cancers." (PMID 32922184, 2020). "It is also reported that NQO1 elevation is a consequence of mutant K-RAS-driven Nrf2 overexpression in cancer cells." (PMID 33214574, 2020). "Detection of NQO1 accurately is of great significance to improve the early diagnosis of cancer and prognosis of cancer patients." (PMID 33005608, 2020). "A pro-oxidant therapy using ROS inducers alone or in combination can be used to specifically damage cancer cells with high NQO1 levels." (PMID 32645959, 2020). "NQO1 is overexpressed in certain types of cancer and its inhibition by dicoumarol (Dic), and analogs thereof, arrests the growth of certain cancer cell lines." (PMID 32825392, 2020). "Given the ubiquitous expression feature of NQO1 33, cancer targeting must be achieved to avoid side effects." (PMID 32922184, 2020). "NQO1 is abnormally overexpressed in most malignant tumors, which contributes to drug resistance by metabolizing xenobiotics to their inactive forms or chemical structures that are excreted out of the cell for chemoprotection." (PMID 32295316, 2020). "β-Lapachone and its derivatives have emerged as a lead class of quinone-based NQO1 bioactivatable therapeutics and radiation sensitizers for numerous cancers." (PMID 33262939, 2020). "The inhibition of NQO1 by dicoumarol increased mitochondrial superoxide and sensitized cancer cells to M/A." (PMID 33204397, 2020). "This has prompted research towards inhibiting NQO1 as a cancer therapy (e.g., Dic effectively inhibits cancer cells growth)." (PMID 33153185, 2020). "Alteration of expression or mutation of different proteins in the BER pathway can either sensitize or protect cancer cells from NQO1-bioactivatable drug-mediated lethality." (PMID 32974194, 2020). "Recently, KP372-1 was identified as a novel NQO1 redox cycling agent that induces cytotoxicity in cancer cells by creating redox imbalance; however, the mechanistic basis of KP372-1-induced cytotoxicity remains elusive." (PMID 33214574, 2020). "Low levels (0 to 1+) of NQO1 were seen in 49% of carcinomas versus 30% and 37% of benign and PIN tissues, respectively (P < 0.05)." (PMID 31909204, 2020). "Upon further analysis of the immunohistochemistry data from the TMA samples, we observed a link between decreased level of NQO1 in carcinoma compared with normal and biochemical recurrence (BCR) following radical prostatectomy." (PMID 31909204, 2020). "In multiple cases, there was a notable decrease in NQO1 level (0 to 1+) in carcinoma compared with PIN from the same patient that showed strong staining (2+ to 3+)." (PMID 31909204, 2020). "Among the NRF2 targets involved in chemotherapeutic resistance, there is catalase, whose overexpression protects cancer cells from apoptosis induced by DNA-damaging agents and NQO1, whose inhibition potentiates the cytotoxicity of anticancer treatments." (PMID 31052524, 2019). "In CCA, NQO1 plays a role in modulating sensitivity of cancer cells to gemcitabine when given in combination with dicoumarol, which enhances gemcitabine cytotoxicity in CCA cells with high NQO1 activity." (PMID 35582588, 2019).
cancer (continued). "Concomitant to increased NRF2 activation, NRF2-target antioxidant enzymes such as GSTs and NQO1 are reportedly upregulated in cancer cells." (PMID 31666108, 2019). "NQO1 has attracted much attention as a potential target for the treatment of cancer because it has been shown to be frequently expressed at much higher levels in tumors, mainly in lung tumors, relative to adjacent non-neoplastic tissue regions." (PMID 31126053, 2019). "Although under NC2 densitometry registers an obvious increase of NQO1 in both IMR-90 fractions, the intensity of the NQO1 signal remained very weak and far below the signal obtained in all cancer cell lines and under all tested conditions." (PMID 31470592, 2019). "High NQO1:Catalase ratios in human cancers can offer an optimal therapeutic window for the use of NQO1 bioactivatable drugs, while low expression ratios protect normal tissues." (PMID 31324798, 2019). "Although all three cancer cell lines had a considerably high level of NQO1 in both cellular fractions, a lower basal amount of NQO1 in Cal 27 nuclear fraction, as compared with FaDu and Detroit 562, was obvious on all our blots." (PMID 31470592, 2019). "This includes the potential to address the dysfunction of the p.P187S variant using small molecules designed to stabilise the protein (pharmacological chaperones) and the design of drugs to inhibit NQO1 specifically in cancer patients." (PMID 30518535, 2019). "To overcome these limitations recently we have developed an NQO1 activated fluorescent probe NQ-DCP with large Stokes shift for cancer cell imaging." (PMID 31189950, 2019). "Would this be the case, overexpression of these enzymes would be crucial for naphthoquinones to exert their action, which would also serve as an explanation towards their selectivity, since enzymes such as NQO1 are reportedly overexpressed in cancer tumors." (PMID 31388334, 2019). "The increase in the NQO1 target gene transcription affected the retinoic acid pathway, and prevent from cancer." (PMID 31207142, 2019). "Such quinones can be exploited as anti-cancer prodrugs which become active when reduced by NQO1 and its high expression in tumour cells ensures that the effects of such prodrugs is largely targeted to these cells." (PMID 31431515, 2019). "We successfully employed the NIR-ASM to differentiate cancer cells from normal cells based on NQO1 activity using fluorescence microscopy and flow cytometry." (PMID 31189950, 2019). "Using clonogenic survival assays, we demonstrated that the expression of NQO1*1, the wild-type form with normal activity, was a main factor of cancer cell resistance vis-à-vis menadione and doxorubicin." (PMID 31480790, 2019). "Here we investigated the mechanism of acquired resistance to a novel anticancer agent RH1 designed to be activated in cancer cells by the NQO1 enzyme." (PMID 31336714, 2019). "Accordingly, several QPA-based fluorescent probes for detection and imaging of NQO1 in cancer cells." (PMID 31189950, 2019). "These cells exhibited a physiological cellular response relating to the activation of NRF2-NQO1 axis during nutritional stress, which resulted with hardly detectable NQO1 signals when compared to the cancer cell lines." (PMID 31470592, 2019). "Under NC3, FaDu was the only cancer cell line which had a significant increase of NQO1 in the nucleus (NC2 vs. NC3 p = 0.0178)." (PMID 31470592, 2019). "Nevertheless, it has been widely reported that NQO1 is overexpressed in cancer tissues, which would serve as a justification for the selectivity of agents targeting this enzyme." (PMID 31388334, 2019). "Since NQO1 protein levels are often increased in tumors as compared to healthy tissues, this enzyme emerges as an attractive target for cancer therapy, because NQO1 bioactivates compounds like β-lapachone leading to a selective cancer cells toxicity." (PMID 31480790, 2019).